LAMTOR1 (late endosomal/lysosomal adaptor, MAPK and MTOR activator 1)
Description:
Key component of the Ragulator complex, a multiprotein complex involved in amino acid sensing and activation of mTORC1, a signaling complex promoting cell growth in response to growth factors, energy levels, and amino acids. Activated by amino acids through a mechanism involving the lysosomal V-ATPase, the Ragulator plays a dual role for the small GTPases Rag (RagA/RRAGA, RagB/RRAGB, RagC/RRAGC and/or RagD/RRAGD): it (1) acts as a guanine nucleotide exchange factor (GEF), activating the small GTPases Rag and (2) mediates recruitment of Rag GTPases to the lysosome membrane. Activated Ragulator and Rag GTPases function as a scaffold recruiting mTORC1 to lysosomes where it is in turn activated. LAMTOR1 is directly responsible for anchoring the Ragulator complex to the lysosomal membrane. LAMTOR1 wraps around the other subunits of the Ragulator complex to hold them in place and interacts with the Rag GTPases, thereby playing a key role in the recruitment of the mTORC1 complex to lysosomes. Also involved in the control of embryonic stem cells differentiation via non-canonical RagC/RRAGC and RagD/RRAGD activation: together with FLCN, it is necessary to recruit and activate RagC/RRAGC and RagD/RRAGD at the lysosomes, and to induce exit of embryonic stem cells from pluripotency via non-canonical, mTOR-independent TFE3 inactivation (By similarity). Also required for late endosomes/lysosomes biogenesis it may regulate both the recycling of receptors through endosomes and the MAPK signaling pathway through recruitment of some of its components to late endosomes. May be involved in cholesterol homeostasis regulating LDL uptake and cholesterol release from late endosomes/lysosomes. May also play a role in RHOA activation.
Synonyms: p27RF-Rho; C11orf59; PDRO; FLJ20625; p18; Ragulator1
Tractability: Small molecule: a structure with a bound ligand is known. Antibody: its Gene Ontology location is reachable by antibodies, with high confidence; the Human Protein Atlas places it where antibodies can reach. PROTAC: UniProt records ubiquitination sites on it; ubiquitination databases record sites on it; its protein half-life has been measured.
Gene: Protein-coding gene on chromosome 11 (72,085,895 to 72,103,297, reverse strand). Ensembl gene ENSG00000149357.
Subcellular location: Lysosome membrane; Late endosome membrane
Subcellular location (Human Protein Atlas): Golgi apparatus; Plasma membrane; Vesicles
Pathways (Reactome):
Signal Transduction: CDC42 GTPase cycle; Energy dependent regulation of mTOR by LKB1-AMPK; MTOR signalling; RAC1 GTPase cycle; RAC2 GTPase cycle; RAC3 GTPase cycle; RHOG GTPase cycle; RHOH GTPase cycle; RHOJ GTPase cycle; RHOQ GTPase cycle; Regulation of PTEN gene transcription; mTORC1-mediated signalling
Autophagy: Macroautophagy
Cellular responses to stimuli: Amino acids regulate mTORC1
Immune System: Neutrophil degranulation
Gene Ontology:
Molecular function: GTPase binding; guanyl-nucleotide exchange factor activity; molecular adaptor activity; protein binding; protein-membrane adaptor activity
Biological process: cellular response to amino acid stimulus; cellular response to nutrient levels; cholesterol homeostasis; intracellular protein localization; positive regulation of protein localization to lysosome; positive regulation of TOR signaling; positive regulation of TORC1 signaling; protein localization to membrane; regulation of cell growth; regulation of cholesterol efflux; regulation of cholesterol import; endosomal transport; endosome organization; lysosome localization; lysosome organization; positive regulation of MAPK cascade; regulation of receptor recycling; TORC1 signaling
Cellular component: extracellular exosome; FNIP-folliculin RagC/D GAP; late endosome membrane; lysosomal membrane; lysosome; plasma membrane; Ragulator complex; azurophil granule membrane; ficolin-1-rich granule membrane; membrane raft; specific granule membrane
Genetic constraint (gnomAD): Loss-of-function variants: 8 observed, 18.14 expected, observed/expected ratio (o/e) 0.44, 90% interval 0.26 to 0.8. The upper end of that interval is the gene's LOEUF score, 0.8, which puts it in group 3 of 6, group 1 being the genes least tolerant of losing a copy. Missense variants: 135 observed, 201.73 expected, observed/expected ratio (o/e) 0.67, 90% interval 0.58 to 0.77. Synonymous variants: 77 observed, 80.06 expected, observed/expected ratio (o/e) 0.96, 90% interval 0.8 to 1.16.
Homologues: Orthologues: chimpanzee LAMTOR1 (100% identical), guinea pig LAMTOR1 (100% identical), rabbit LAMTOR1 (100% identical), mouse Lamtor1 (99% identical), dog LAMTOR1 (99% identical), rat Lamtor1 (98% identical), rat Lamtor1l1 (98% identical), pig LAMTOR1 (93% identical), macaque LAMTOR1 (93% identical), zebrafish lamtor1 (68% identical), tropical clawed frog lamtor1 (47% identical), Drosophila melanogaster Lamtor1 (37% identical).
Diseases named in the same sentence as LAMTOR1 in open-access papers:
LAMTOR1 is named in the same sentence as 34 diseases in open-access papers, as found by Europe PMC text mining. Sharing a sentence is not in itself a finding about the gene and the disease. The quoted sentences say what the papers report.
colorectal cancer (3 papers, 2024 to 2025). A primary or metastatic malignant neoplasm that affects the colon or rectum. "Lamtor1 facilitates the activation of mTORC1, influencing the advancement of colorectal cancer (CRC) induced by inflammation." (PMID 39452097, 2024). "Additionally, the TRAF4-mediated ubiquitination of LAMTOR1 drives mTORC1 activation in colorectal cancer, suggesting that TRAF4 inhibitors could suppress oncogenic signaling." (PMID 40427667, 2025). "Functionally, the ubiquitination of LAMTOR1 regulates the interaction between Ragulator and Rag GTPases and enhances the GEF activity of Ragulator toward RagC/D, which in turn promotes the activation of mTORC1 and affects the progression of inflammation‐induced colorectal cancer (CRC)." (PMID 38229144, 2024).
Angelman syndrome (2 papers, 2023 to 2024). A neurogenetic disorder characterized by severe intellectual deficit and distinct facial dysmorphic features. "We recently reported that LAMTOR1 is a target of the UBE3A ubiquitin ligase, which is downregulated in Angelman syndrome (AS), thereby implicating changes in lysosomal distribution, function and mTOR signaling in the etiology of AS." (PMID 39650798, 2024).
bladder cancer (2 papers, 2023 to 2024). "For example, the myristoylation of LAMTOR1 at Gly2 increases the stability of LAMTOR1 and its lysosomal localization, which is critical for mTORC1 activation, autophagy and bladder cancer growth." (PMID 39883197, 2024).
colon cancer (2 papers, 2023 to 2024). "Surprisingly, using a mouse model, we found that TRAF4 inhibits inflammation‐induced colon cancer progression, possibly via the ubiquitination of LAMTOR1." (PMID 38229144, 2024). "In conclusion, we propose a mechanistic model in which Ragulator‐mediated mTORC1 activation is regulated by the TRAF4‐catalyzed ubiquitination of LAMTOR1 at K151, which regulates the development of inflammation‐induced colon cancer." (PMID 38229144, 2024). "Ubiquitination of LAMTOR1 by TRAF4 promoted its binding to Rag GTPases and enhanced mTORC1 activation, K151R knock‐in or TRAF4 knock‐out blocks amino acid‐induced mTORC1 activation and accelerates the development of inflammation‐induced colon cancer." (PMID 38229144, 2024).
hepatocellular carcinoma (2 papers, 2021 to 2025). A malignant tumor that arises from hepatocytes. "According to data from the TCGA database, LAMTOR1 is highly expressed in various malignant tumors, such as hepatocellular carcinoma (HCC) and colon adenocarcinoma (COAD)." (PMID 40427667, 2025). "Public gene expression data shows that the expression of LAMTOR1 is abnormally high in nonalcoholic steatohepatitis (NASH) and hepatocellular carcinoma (HCC); hence, LAMTOR1 may play an important role in the development of NASH and HCC." (PMID 34505434, 2021).
Obesity (2 papers, 2021 to 2026). Accumulation of substantial excess body fat. "Overall, our results suggest that LAMTOR1 deficiency in macrophages prevents obesity and metabolic disorders via the accumulation of Kupffer cells in the liver and the consequent hyper-inflammation and increased energy expenditure." (PMID 34095141, 2021). "We found that LAMTOR1 MKO mice were resistant to obesity and metabolic disorders with an elevation in energy expenditure." (PMID 34095141, 2021). "LAMTOR1 MKO mice showed resistance to high-fat diet (HFD)-induced obesity, lipid steatosis, and glucose metabolic disorders, with elevated levels of pro-inflammatory cytokines." (PMID 34095141, 2021). "In this study, we explored the effect of macrophage LAMTOR1 on diet-induced obesity and glycolipid metabolism." (PMID 34095141, 2021). "Our findings further showed an upregulation of LAMTOR1 and PLTP (phospholipid transfer protein) in severe obesity." (PMID 41077621, 2026). "However, when fed with an HFD, LAMTOR1 MKO mice showed a significant decrease in the body weight and white adipose tissue (WAT) mass, as well as a smaller liver (vs. WT mice), suggesting the macrophage-specific depletion of LAMTOR1 was able to prevent HFD-induced obesity." (PMID 34095141, 2021).
acute promyelocytic leukemia (1 paper, 2025). An aggressive form of acute myeloid leukemia (AML), characterized by arrest of leukocyte differentiation at the promyelocyte stage, due to a specific chromosomal translocation t(15;17) in myeloid cells. "LAMTOR1 is a member of Ragulator-Rag GTPase complex, which may provide a platform for nutrient sensing on lysosomes and has been shown in vitro to be regulated by epigenetic treatment in acute promyelocytic leukemia." (PMID 40868343, 2025).
Autoimmunity (1 paper, 2022). The occurrence of an immune reaction against the organism's own cells or tissues. "Mice with Lamtor1-deficient Treg cells develop severe autoimmunity showing that Lamtor1 is a vital intrinsic factor for Treg suppressive functions, but not for their development and survival." (PMID 35693798, 2022).
cognitive disorder (1 paper, 2024). A disease affects cognitive processes. "The roles of LAMTOR1-TRPML1 interactions in lysosomal trafficking and positioning could have broad implications for understanding cognitive disorders associated with lysosomal pathology and calcium dysregulation." (PMID 39650798, 2024).
COVID-19 (1 paper, 2024). A disease caused by infection with severe acute respiratory syndrome coronavirus 2. "In this work, we identified an increased expression of lysosomal genes such as LAMTOR1, NEU1, GBA1, BORCS8, and BLOC1S1 in severe COVID-19 patients." (PMID 38262689, 2024).
dysferlinopathy (1 paper, 2023). "Analysis of muscle transcripts from patients with dysferlinopathy helped identify the following 7 upregulated DEGs involved in the cellular response to stress: HSPA9, RPTOR, MTOR, LAMTOR1, LAMTOR5, ATP6V0D1, and ATP6V0B." (PMID 38125829, 2023).
Infertility (1 paper, 2018). "The biological processes significantly represented among differentially expressed genes included mitochondrial function (Mrps31 and Trit1), cell senescence (Gpx6, Lamtor1 and Hist1h1e), cell growth (Hormad1 and Hormad2), infertility (Sycp3), and embryo development (Gli3)." (PMID 29851234, 2018).
liver disease (1 paper, 2025). "This suggests that LAMTOR1 may serve as a potential risk factor for the development of liver disease in humans." (PMID 40548398, 2025).
lymphoma (1 paper, 2020). A malignant (clonal) proliferation of B- lymphocytes or T- lymphocytes which involves the lymph nodes, bone marrow and/or extranodal sites. "We also detected changes in the expression of proteins involved in the proliferation-related mTOR and NF-κB pathways, such as LAMTOR1 and NFKBID, which was consistent with a previous study describing a multiprotein supercomplex involved in the control of oncogenic signaling in lymphoma." (PMID 32546241, 2020).
prostate carcinoma (1 paper, 2015). A carcinoma that arises from epithelial cells of the prostate gland. "Other promising prostate cancer biomarkers are LAMTOR1 and ADIRF (81% sensitivity at 100% specificity)." (PMID 26196085, 2015).
Salmonella Infections (1 paper, 2020). Infections with bacteria of the genus SALMONELLA. "In addition, they identified LAMTOR2 and LAMTOR1 as previously overlooked xenophagy regulators of TAX1BP1 in response to Salmonella infection, and confirmed that LAMTOR2 was recruited to damaged SCVs via LAMTOR1, an endosome-resident protein." (PMID 32390979, 2020).
Sepsis (1 paper, 2016). Sepsis is defined as life-threatening organ dysfunction caused by a dysregulated host response to infection. "Next, to examine the importance of Lamtor1 in innate immune response in vivo, we used an LPS-induced sepsis model." (PMID 27731330, 2016).
cancer (9 papers, 2015 to 2026). A tumor composed of atypical neoplastic, often pleomorphic cells that invade other tissues. "LAMTOR1 is involved in amino acid sensing and activation of mTORC1, a gene strongly associated with aging and cancer." (PMID 25565328, 2015). "As a protein with increased binding in KRAS G12C/D/V mutation groups, LAMTOR1 may emerge as a potential therapeutic target for cancer treatment." (PMID 40427667, 2025). "The relationship between N-myristoyltransferase-1 (NMT1), which functions as an oncogene in various cancers, and Lamtor1 has been emphasized in cancer biology by several groups." (PMID 37173755, 2023). "The cluster for GC versus GIN was mostly related to energy metabolism, cancer metastasis, and invasions, such as LAMTOR1 and TOM1." (PMID 35958927, 2022). "The specific mechanism by which NMT1 and LAMTOR1 promote lysosomal degradation in cancer cells remains to be determined." (PMID 32686708, 2020). "The lysosomal regulator complex member LAMTOR1 serves as a crucial pivot that recruits the mechanistic target of rapamycin complex 1 (mTORC1) to the lysosomal surface, thereby influencing biological processes such as cell growth and cancer progression." (PMID 41856969, 2026). "However, the exact mechanism by which NMT1 and LAMTOR1 promote lysosomal degradation in cancer cells remains to be determined." (PMID 37140999, 2023). "Inhibition of NMT using a small compound decreased cancer cell viability in vitro and in vivo through inhibition of mTORC1 and simultaneous blockade of lysosomal degradation, mostly through inactivation of the lysosomal adaptor LAMTOR1." (PMID 32686708, 2020). "Particularly, the key regulators of mTOR signaling such as LAMTOR2, LAMTOR5, YWHAB, LAMTOR1, FKBP1A, and RHEB were also upregulated in the cancer cells of intra‐tumoral TLS‐low group." (PMID 38498682, 2024). "Depletion of LAMTOR1 was reported to increase lysosomal abundance without decreasing lysosomal degradation in cancer cells." (PMID 32686708, 2020). "Collectively, these findings indicate that sustained NMT1 activity is necessary for LAMTOR1-dependent lysosomal localization of mTORC1, and that lysosomal mTORC1 localization and activation can be effectively disrupted with a small molecule inhibitor of NMT in cancer cells." (PMID 32686708, 2020). "Our finding that TFE3 further accumulates in the nucleus of cancer cells lacking NMT1, LAMTOR1, or in cells treated with NMTi is consistent with both the inhibition of mTORC1 activity by NMTi, and the autophagy blockade provoked by the lack of degradative lysosomal activity." (PMID 32686708, 2020).
tumor (4 papers, 2023 to 2025). "TMEM127, a tumor suppressor gene, interacts with the Ragulator complex in an amino acid-dependent manner and decreases the LAMTOR1-vATPase association." (PMID 37173755, 2023). "Neurofibromin, a tumor suppressor, forms a protein complex with LAMTOR1 and inhibits mTOR signaling." (PMID 37173755, 2023). "Recent studies have explored molecular determinants of immunotherapy response: for example, LAMTOR1 was shown to inhibit PD-L1 exosomal secretion, thereby enhancing anti-tumor immunity.while metabolic reprogramming was linked to immune checkpoint inhibitor (ICI) efficacy." (PMID 40888963, 2025). "However, LAMTOR1 K151R KI mice showed a higher number of tumor colonies, shorter colon length, and larger tumor size than in WT mice in an AOM/DSS inflammation‐induced CRC." (PMID 38229144, 2024). "By the regulation of the endocytic pathway, LAMTOR1 decreases the expression of MHC-II on cell surfaces, resulting in reduced antigen expression in anti-tumor immunity." (PMID 37173755, 2023).
metabolic disorders (3 papers, 2021 to 2025). "In conclusion, we identified LAMTOR1 as a biologically relevant target for ACA in the reduction of metabolic disorders." (PMID 40548398, 2025). "These metabolic disorders demonstrated that LAMTOR1 significantly contributed to the metabolic mechanism of NASH." (PMID 34505434, 2021). "Except for the systematic hyper-inflammation and improvement of metabolic disorders, we also found the aggregation of Kupffer cells in the livers of LAMTOR1 MKO mice." (PMID 34095141, 2021). "This study highlights the critical role of LAMTOR1 in metabolic regulation and suggests that targeting LAMTOR1 may represent a promising strategy for metabolic disorders, including MAFLD." (PMID 40548398, 2025). "In this study, we identified LAMTOR1 as the target of ACA, a natural compound that regulates metabolic disorders through autophagy." (PMID 40548398, 2025).
infection (2 papers, 2017 to 2022). The state of being infected such as from the introduction of a foreign agent such as serum, vaccine, antigenic substance or organism. "To test whether BORC-related lysosome trafficking components mediate BCV trafficking during infection, we analyzed the dynamics of the interaction of BCVs with LAMTOR1 (a central component of mTORC1), the small GTPase ARL8b, and kinesin KIF1b and KIF5b proteins during infection." (PMID 35587649, 2022). "Nevertheless, we detected a significant decrease in the recruitment of Lamtor1, Rheb and Lst8 to the M. marinum ΔRD1 MCV at 7 hpi, suggesting that the features of the bacterial compartment diverge during infection depending on the functionality of the ESX-1 system." (PMID 28414774, 2017).
bacterial infection (1 paper, 2023). "LAMTOR1 was localized to bacterium-containing endosomes, and LAMTOR2 was recruited to damaged bacterium-containing endosomes in a LAMTOR1-dependent manner, facilitating autolysosome formation during bacterial infection." (PMID 37173755, 2023).
LAMTOR1 also shares sentences with these, for which no sentence is quoted: breast carcinoma (2 papers); acute lymphoid leukemia (1); acute myeloid leukemia (1); Batten disease (1); colon adenocarcinoma (1); Glucose Metabolic Disorders (1); hyperplasia (1); Insulin resistance (1); lung carcinoma (1); Myelodysplasia (1); ovarian carcinoma (1); renal cell carcinoma (1).